DNA2 (DNA replication helicase/nuclease 2)
Diseases named in the same sentence as DNA2 in open-access papers (continued):
Sharing a sentence is not in itself a finding about the gene and the disease.
cancer (continued). "Treatment of cancer cells with DNA2 inhibitors recapitulates phenotypes observed upon DNA2 depletion, including decreased DNA double strand break end resection and attenuation of HR repair." (PMID 28414320, 2017). "It was observed that enhanced expression of DNA2 occurred in an early stage of cancer transformation in a cell model with K-RAS (Kirsten rat sarcoma viral oncogene homolog) activation." (PMID 28718810, 2017). "It was shown that DNA2 was significantly overexpressed in pancreatic cancer cell lines, and its inhibition resulted in a lower survival of cancer cells and a decreased growth of their xenografts." (PMID 28718810, 2017). "We propose DNA2 inhibition as new strategy in cancer therapy by targeting replication stress, a molecular property of cancer cells that is acquired as a result of oncogene activation instead of targeting currently undruggable oncoprotein itself such as KRAS." (PMID 28414320, 2017). "Nuclear localization of DNA2 was observed in normal and primary cancer cells as well as in cell lineages." (PMID 28718810, 2017). "Enhanced DNA2 expression was also observed strongly in cell lines with atypical hyperplasia, a premalignant state typical for many cancers." (PMID 28718810, 2017). "Cancer microarray data identified enhanced expression of DNA2 at mRNA and protein levels in cancer cells." (PMID 28718810, 2017). "The role of DNA2 in telomere end maintenance and cell cycle regulation suggests its more general role in keeping genomic stability, which is impaired in cancer." (PMID 28718810, 2017). "Treatment of cancer cells with the top DNA2 inhibitor recapitulates many phenotypes observed upon DNA2 depletion, and attenuates the growth of various cancer cells." (PMID 28414320, 2017). "This is supported by enhanced expression of DNA2 in many cancer cell lines with oncogene activation and premalignant cells." (PMID 28718810, 2017). "DNA2 overexpression, often observed in cancer cells, has been proposed to alleviate oncogene-induced replication stress." (PMID 28414320, 2017). "In our study we elaborated on the role of DNA2 in estrogen-dependent cancers and showed that DNA2 expression is not only increased but also reduced in cancer cells." (PMID 25238049, 2014). "However, mice heterozygous for DNA2 loss-of function mutations are viable, which suggests that there is a therapeutic window to inhibit DNA2 activity in the context of cancers with DNA2 overexpression, such as MM that has relapsed after PI-based treatment." (PMID 38331987, 2024). "Given that metabolic reprogramming is a hallmark of cancer progression, further studies will clarify whether therapeutically targeting DNA2 has a broad spectrum of anti-cancer applications." (PMID 38331987, 2024). "Therefore, FEN1 or DNA2 inhibitors can induce synthetic lethality with BRCA1/2 deficiency and/or with PARPi in human cancer cells." (PMID 38714348, 2024). "Interestingly, DNA2 protein levels are upregulated at an early stage of transformation in a broad range of cancer cells." (PMID 37756561, 2023). "Thus, it would be highly interesting to explore the cellular localization of TERT and DNA2 in various cancers and in the context of hypoxia." (PMID 37418389, 2023). "DNA2 have functions as both a tumor promoter and suppressor in cancers." (PMID 36685880, 2022). "Overexpression of DNA2 is reported in multiple human cancers." (PMID 34181336, 2021). "This suggests that DNA2 could play a role in supporting cancer-cell proliferation, most likely through its ability to offset replication stress." (PMID 33924313, 2021). "In addition, DNA2 over-expression has been observed in cancer and the protein is emerging as a potential target for anti-cancer therapy." (PMID 33924313, 2021). "Increased expression of DNA2 could therefore reflect an adaptation of cancer cells that helps them cope with elevated levels of endogenous replication stress and increased requirements for RF recovery and DNA repair." (PMID 33924313, 2021).
cancer (continued). "Consistent with this hypothesis, heterozygous Dna2 knockout mice have relatively high spontaneous cancer incidence compared to wild-type mice." (PMID 31754720, 2020). "Furthermore, DNA2 is overexpressed in several human cancers and has been found to support cancer cell survival by counteracting DNA replication stresses." (PMID 31754720, 2020). "One important function of mammalian DNA2 is to facilitate DNA replication at telomeres and centromeres, and its dysfunction at these critical structures may promote the development of cancer." (PMID 31754720, 2020). "In cancer, DNA2 has been found overexpressed, potentially providing a survival advantage under elevated replication stress, which is prevalent in cancer cells." (PMID 32909097, 2020). "Finally, the observed overexpression of DNA2 in cancer likely reflects an adaptation to increased levels of intrinsic RS, which is prominent in cancer cells." (PMID 32544229, 2020). "Thus, inhibiting specific DNA replication and repair proteins like DNA2 has been an attractive anti-cancer strategy." (PMID 31754720, 2020). "However, DNA2-mediated pathways that counteract replication stresses and repair DSBs are also utilized to promote cancer cell survival." (PMID 31754720, 2020). "Supporting this hypothesis, recently developed small molecule DNA2 inhibitors have been shown to kill and sensitize cancer cells to ionizing radiation and camptothecin." (PMID 31754720, 2020). "Furthermore, the DNA2 inhibitor C5 mimics DNA2 knockout and synergistically kills cancer cells when combined with an ATR inhibitor." (PMID 29773570, 2018). "This raises the question about the clinical significance of DNA2 in cancer." (PMID 28718810, 2017). "As such stress is a common denominator among multiple cancer types, DNA2 inhibition could be an efficacious strategy to treat a broad spectrum of cancers." (PMID 28414320, 2017). "Therefore, a new target in cancer therapy can be considered—DNA2, whose inhibition can result in eradication of cancer cells following from their decreased ability to repair DSBs produced by oncogene-activated replication stress." (PMID 28718810, 2017). "As the increased nuclease activity of DNA2 is required in yeast and cancer cells to overcome replication stress and DNA damage, for the first time, we developed a robust biochemistry-based screening method for chemical inhibitors of DNA2." (PMID 28414320, 2017). "Therefore, DNA2 can be considered as a molecular target in such cancers, both directly and in synthetic lethality." (PMID 28718810, 2017). "We have presented evidence that DNA2 overexpression alleviates the impaired proliferation of U2OS and MCF10A cells after an activation of either H-Ras or cyclin E,33 suggesting that DNA2 could be an effective target in cancer therapy." (PMID 28414320, 2017). "In addition, BRCA1 has been implicated in DNA2 recruitment to double-stranded DNA breaks, suggesting that BRCA1-deficent cancer cells might have lower levels of DNA2 localized to stalled and/or reversed replication intermediates." (PMID 38943334, 2024). "Moreover, we also uncover that loss of EXD2 is synthetic sick with BLM, DNA2 and POLD3, which could represent an attractive therapeutic target against ALT-dependent cancers." (PMID 37105990, 2023). "Importantly, DNA2 has been identified as a candidate for targeted cancer therapy." (PMID 33924313, 2021). "Interestingly, an involvement of DNA2 in ameliorating telomere-specific replication stress echoes with observations in cancer cells that use a recombination-based mechanism, alternative lengthening of telomeres (ALT), for telomere maintenance in lieu of telomerase reactivation." (PMID 33924313, 2021). "Thus, DNA2 high expression may promote the proliferation of cancer cells, and targeting DNA2 may be a new cancer therapy." (PMID 33574966, 2021).
cancer (continued). "Therefore, although, like other current chemotherapeutics, inhibitors of DNA2 may potentially initiate new cancers, DNA2 has been suggested as a cancer therapeutic target." (PMID 31754720, 2020). "Importantly, this function of DNA2 may play a major role in tolerance to chronic replication stress, induced e.g., by oncogene activation, commonly exhibited by cancer cells." (PMID 32432041, 2020). "Therefore, DNA2 may serve as a target for killing cancer cells or sensitizing cancer cells to existing chemotherapeutic agents." (PMID 31754720, 2020). "Deletion of DNA2 genes in human HCT116 cells resulted in incomplete DNA replication at centromeres, causing dysfunctional centromeres and chromosome segregation errors that led to aneuploidy, a hallmark of many human cancers that facilitates cancer development." (PMID 31754720, 2020). "However, DNA2 may also function as a tumor promoter, supporting cancer cell survival by counteracting replication stress." (PMID 31754720, 2020). "Thus, inhibiting DNA2 may simultaneously impair the ability of cancer cells to handle DNA replication stress and DSBs, leading to apoptosis and cellular senescence." (PMID 31754720, 2020). "Therefore, DNA2 inhibitors and their potential synergy with other chemotherapeutics may provide new, more effective cancer treatment regimens." (PMID 29773570, 2018). "Dna2, checkpoint proteins, Pif1 and Mph1 helicases, and Pol32 are all conserved between human and yeast cells, and affect telomere-related human diseases such as cancer, suggesting our observations may be relevant to human disease." (PMID 29559500, 2018). "Therefore, DNA2 can be considered as a potential marker, useful in cancer therapy." (PMID 28718810, 2017). "Therefore DNA2 can be an attractive target in cancer therapy." (PMID 28718810, 2017). "Besides targeting cancer cells with an activated oncogene, chemical inhibition of DNA2 may also be useful for sensitizing cells to DNA damage when combined with radiomimetic chemotherapy or radiation therapy." (PMID 28414320, 2017). "The expression levels of DNA2 and MYO19 were significantly upregulated in FDPS at stages 1, 2, 3, and 4 according to individual cancer stage." (PMID 40839681, 2025). "Due to their dual roles in DNA replication and DSB repair, DNA2 and EXO1 are not only two exceptional targets for cancer cell-specific killing, but also two outstanding targets for inducing synthetic lethality of cancer cells." (PMID 38714348, 2024). "Experimentally, DNA2 has been shown to promote cancer cell survival following overexpression of H-RAS or Cyclin E, suggesting a role for DNA2 in overcoming oncogene-induced replication stress." (PMID 33924313, 2021). "Due to the critical roles of DNA2 in DNA replication and DSB repair, it has been proposed as an ideal target to sensitize cancer cells to chemotherapy or radiotherapy treatment." (PMID 31754720, 2020). "If the activation of ATR in DNA2 null cells is to overcome endogenous replicative stresses at the centromeric DNA region as previously suggested, targeting both DNA2 and ATR will generate synergy in cancer treatment." (PMID 29773570, 2018). "The discovery that mutations, which occurred in cancer cases did not complement the yeast phenotype at all, or partially complemented the phenotype compared to the WT human DNA2, demonstrates that these mutations impair DNA2 activity (either full or partial impairment)." (PMID 25238049, 2014). "Finally, we show that co-depletion of EXD2 with BLM, DNA2 or POLD3 confers synthetic lethality in ALT cells, identifying EXD2 as a potential druggable target for ALT-reliant cancers." (PMID 37105990, 2023).
cancer (continued). "Furthermore, as DNA2 plays a role in DSB repair via HR pathways, the combination of d16 and PARPis can be utilized as a synthetic lethal therapy in BRCA1- and or BRCA2-proficient cancer cells and xenografts." (PMID 37756561, 2023). "For example, more EA80 VUS cluster in the DNA2 helicase domain than its nuclease domain, implying that its replication fork recovery role may be targeted by cancers rather than its DNA-end resection function." (PMID 34966786, 2021). "Therefore, simultaneous inhibition of DNA2 and ATR could have an additive or synergistic effect in killing cancer cells." (PMID 29773570, 2018).
tumor (23 papers, 2012 to 2025). "Our findings indicate that the expression of mitochondrial MYO19 and DNA2 is significantly associated with the tumor infiltration of various immune cells, including B cells, T cells (CD8+ and CD4+), neutrophils, macrophages, and dendritic cells." (PMID 40839681, 2025). "In addition, DNA2 expression was associated with multiple immune cell infiltrations, indicating a very strong tumor relevance." (PMID 40839681, 2025). "It was found that overexpressed DNA2 promotes tumor cell survival by overcoming replication stress on DNA replication forks induced by chemotherapy or radiotherapy." (PMID 38586304, 2024). "We found that plasma circ-CYP24A1, circ-ALDH3A2 and circ-DNA2 levels displayed correlations to maximum tumor diameter, tumor thickness, preoperative serum SCC-Ag and serum SCC-Ag 1 month after surgery." (PMID 34109199, 2021). "Through these versatile activities at replication forks and DNA damage sites, DNA2 functions as both a tumor suppressor and promoter." (PMID 31754720, 2020). "Consistent with in vitro cell culture findings, DNA2 knockdown significantly reduced tumor growth in the xenograft model." (PMID 28414320, 2017). "With tumor development, the expression of DNA2 gradually increased." (PMID 40839681, 2025). "Therefore, our ET/EA analyses on VUS reveal RPA functional interactions and a critical role of DNA2 helicase activity that act synergistically not only for genome stability but evidently also for tumor viability." (PMID 34966786, 2021). "Interestingly, DNA2 functions as both a tumor suppressor and promoter." (PMID 31754720, 2020). "The expression levels of DNA2 and MYO19 were relatively higher in HCC patients with tumor grade 3 compared with tumor grades 1 and 2 (P < 0.05)." (PMID 40839681, 2025). "Other genes such as RBBP4, DNA2, AP2B1, etc. may also affect tumor immune responses through their respective molecular functions." (PMID 39083127, 2024). "DNA2, along with PARP1 inhibition, may be considered as a potential target for inducing synthetic lethality, a concept of killing tumor cells by targeting two essential genes." (PMID 28718810, 2017). "Finally, the polymerases DNA2 and POLE2 appeared to be deregulated in the telomere pathway in a large number of tumours." (PMID 28387377, 2017).
mitochondrial disease (3 papers, 2020 to 2024). "However, variants have also been described in the dual‐localised nucleases RNASEH1 and DNA2 that result in mitochondrial disease phenotypes." (PMID 37013609, 2023). "With the exception of SSBP1, a key component of the mitochondrial replication fork, to date, all nuclear genes directly involved in mtDNA replication (POLG, POLG2, TWINKLE, RNASEH1, DNA2, MGME1) have been associated with mitochondrial disease, mtDNA depletion, and/or mtDNA deletion." (PMID 31550237, 2020).
DNA2 also shares sentences with these, for which no sentence is quoted: thyroid cancer (3 papers); endometrial cancer (2); Bloom syndrome (1); breast tumors (1); diabetes (1); genetic disorders (1); infection (1); Kindler syndrome (1); liver cancer (1); Mitochondrial myopathy (1); mtDNA depletion syndrome (1); myopathy (1); myopia (1); neuromuscular disease (1); neuropathy (1); neutropenia (1); non–small cell lung cancer (1); osteosarcoma (1); ptosis (1); rectum adenocarcinoma (1); Rothmund-Thomson syndrome (1); stomach adenocarcinoma (1); testis cancer (1); uterine cancer (1); uterine corpus endometrial carcinoma (1); viral infection (1); Werner syndrome (1).